POF1B (POF1B actin binding protein)
Description:
Plays a key role in the organization of epithelial monolayers by regulating the actin cytoskeleton. May be involved in ovary development.
Synonyms: POF; FLJ22792; POF2B
Tractability: PROTAC: ubiquitination databases record sites on it.
Gene: Protein-coding gene on chromosome X (85,276,746 to 85,379,755, reverse strand). Ensembl gene ENSG00000124429.
Subcellular location: Cell junction, tight junction
Subcellular location (Human Protein Atlas): Golgi apparatus; Nucleoplasm
Gene Ontology:
Molecular function: actin filament binding
Biological process: actin cytoskeleton organization; actin filament organization; bicellular tight junction assembly; epithelial cell morphogenesis
Cellular component: actin filament; adherens junction; bicellular tight junction; desmosome; Golgi apparatus
Homologues: Orthologues: chimpanzee POF1B (99% identical), macaque POF1B (97% identical), rabbit POF1B (90% identical), mouse Pof1b (89% identical), rat Pof1b (89% identical), pig POF1B (87% identical), dog POF1B (86% identical), guinea pig POF1B (83% identical), tropical clawed frog pof1b (39% identical), zebrafish pof1b (26% identical).
Diseases named in the same sentence as POF1B in open-access papers:
POF1B is named in the same sentence as 19 diseases in open-access papers, as found by Europe PMC text mining. Sharing a sentence is not in itself a finding about the gene and the disease. The quoted sentences say what the papers report.
premature ovarian failure (8 papers, 2013 to 2024). "POF1B was located in the critical region for normal ovarian function and participated in encoding premature ovarian failure." (PMID 37397364, 2023). "Disruption of HDX, encoding a highly divergent homeobox protein with DNA-binding activity, and POF1B, encoding an actin-binding protein, have both been associated with premature ovarian failure." (PMID 31514470, 2019). "It is notable that Pof1b, the gene named for its association with premature ovarian failure (i.e. POI), is linked to follicle assembly in the current study." (PMID 23875758, 2013). "We identified CBX2 regulated genes associated with polycystic ovary syndrome (PCOS) such as TGFβ, MAP3K15 and DKK1, as well as genes implicated in premature ovarian failure (POF) (i.e. POF1B, BMP15 and HOXA13) and the pituitary deficiency (i.e. LHX4 and KISS1)." (PMID 31745224, 2019). "In addition, three genes (DIAPH2, AFF2, POF1B) were involved in functions related to premature ovarian failure." (PMID 24422716, 2014). "Additionally deleted in both our families are POF1B, which seems to play a role in the etiology of premature ovarian failure, and DACH2, with an important role in the regulation of brain and limb development and presumed to be implicated in syndromic mental retardation." (PMID 34440285, 2021).
lung adenocarcinoma (2 papers, 2025). A carcinoma that arises from the lung and is characterized by the presence of malignant glandular epithelial cells. "Recent studies have found that abnormal POF1B expression plays a significant role in the progression, invasion, and prognosis of squamous cell carcinoma, mucinous ovarian tumors, colorectal cancer, bladder cancer, and lung adenocarcinoma." (PMID 40606178, 2025). "POF1B is mainly expressed in polarized epithelial tissues, and the aberrant expression of POF1B is closely related to malignant tumors such as cutaneous squamous cell carcinoma and lung adenocarcinoma." (PMID 41578779, 2025).
dementia (1 paper, 2025). Loss of intellectual abilities interfering with an individual's social and occupational functions. "Significantly associated proteins at a false discovery rate (FDR) < 0.05 in both models 1 and 2 were CGREF1, MET, ALDH2, NECTIN2, APOC1, APOE and FOSB for HFRS, and CDK and POF1B for HFRS without dementia." (PMID 40764432, 2025).
gastric adenocarcinoma (1 paper, 2025). "Our preliminary experiments have found that POF1B protein expression was higher in AGS (poorly differentiated gastric adenocarcinoma epithelial cell) cells than that in GES-1 (normal epithelial immortalized cell) cells." (PMID 40606178, 2025).
gastric cancer (1 paper, 2025). A primary or metastatic malignant neoplasm involving the stomach. "Pure cultures were used to infect AGS gastric cancer cells, followed by protein extraction and Western blotting to detect POF1B protein expression." (PMID 40606178, 2025). "Based on the analysis of TCGA and GTEx databases using the GEPIA, it was found that the expression of the POF1B gene is significantly higher in gastric cancer tissues." (PMID 40606178, 2025). "So, after gastric cancer cells were infected with these bacteria, the POF1B expression were measured." (PMID 40606178, 2025). "However, the results suggested that P. acnes led to increased POF1B expression in gastric cancer cells, whether this may be one of the mechanisms by which this bacterium promotes gastric cancer progression needs further validation in animal models and clinical cases." (PMID 40606178, 2025).
ischemic stroke (1 paper, 2023). A stroke disorder caused by obstruction of blood flow to the brain, due to thrombotic (local blood clot formation) or embolic (due to a blood clot or other material traveling from another site) event. "With regard to Pof1b (or human POF1B), its gene expression in blood has been associated with ischemic stroke in humans." (PMID 38132326, 2023).
liver cancer (1 paper, 2025). An epithelial or non-epithelial malignant neoplasm that arises from the liver. "The analysis of TCGA liver cancer data showed that the expressions of AGFG1, IQGAP3, SPINK1, CXCL9, MYO1E, and POF1B were significantly increased in tumor tissues." (PMID 41578779, 2025).
cancer (4 papers, 2011 to 2025). A tumor composed of atypical neoplastic, often pleomorphic cells that invade other tissues. "Among these, P. acnes were found to increase POF1B expression of the cancer-related protein." (PMID 40606178, 2025). "POF1B has no known, previous connection to NBL and little connection to cancer in general." (PMID 30962767, 2019).
tumor (3 papers, 2018 to 2025). "Normal tissues exhibited higher levels of S100A9, FTCD, POF1B, IL7R, and MYO1E, whereas tumor tissues showed increased expressions of SPINK1, CXCL9, AGFG1, and IQGAP3." (PMID 41578779, 2025). "Expression of eight additional genes associated with EMT was initially analyzed individually; a good correlation between tumor sensitivity to BI 853520, and gene expression was observed for MUC13 and POF1B but not for TWIST1." (PMID 29472531, 2018).
POF1B also shares sentences with these, for which no sentence is quoted: ovarian failure (2 papers); bladder cancer (1); colorectal cancer (1); cutaneous squamous cell carcinoma (1); mucinous ovarian tumors (1); neurodevelopmental disorder (1); pituitary deficiency (1); polycystic ovary syndrome (1); primary ovarian insufficiency (1); squamous cell carcinoma (1).